RN7SL635P (RNA, 7SL, cytoplasmic 635, pseudogene)
Gene: Miscellaneous RNA gene on chromosome 2 (65,545,401 to 65,545,696, reverse strand). Ensembl gene ENSG00000243029.
Homologues: Orthologues: chimpanzee Metazoa_SRP (100% identical), macaque Metazoa_SRP (93% identical). Paralogues in human: RN7SL1 (81% identical), RN7SL2 (80% identical), RN7SL478P (80% identical), RN7SL3 (79% identical), RN7SL451P (79% identical), RN7SL230P (79% identical), RN7SL556P (79% identical), RN7SL664P (79% identical), RN7SL804P (79% identical), RN7SL712P (78% identical), RN7SL127P (78% identical), RN7SL126P (78% identical), and 702 more.